UTY (ubiquitously transcribed tetratricopeptide repeat containing, Y-linked)
Description:
Male-specific histone demethylase that catalyzes trimethylated 'Lys-27' (H3K27me3) demethylation in histone H3. Has relatively low lysine demethylase activity.
Synonyms: KDM6C; KDM6AL; UTY1
Tractability: Small molecule: a structure with a bound ligand is known. PROTAC: ubiquitination databases record sites on it.
Gene: Protein-coding gene on chromosome Y (13,234,577 to 13,480,673, reverse strand). Ensembl gene ENSG00000183878.
Subcellular location: Nucleus
Subcellular location (Human Protein Atlas): Nucleoplasm; Nucleoli; Nucleoli rim
Pathways (Reactome):
Chromatin organization: HDMs demethylate histones
Gene Ontology:
Molecular function: chromatin DNA binding; histone demethylase activity; histone H3K27me2/H3K27me3 demethylase activity; RNA polymerase II cis-regulatory region sequence-specific DNA binding
Biological process: heart development; regulation of gene expression; chromatin remodeling
Cellular component: MLL3/4 complex; nucleoplasm; nucleus
Homologues: Orthologues: chimpanzee UTY (98% identical), macaque UTY (95% identical), tropical clawed frog kdm6a (80% identical), dog UTY (72% identical), zebrafish kdm6a (70% identical), mouse Uty (68% identical), rat Uty (66% identical), Drosophila melanogaster Utx (36% identical), Caenorhabditis elegans utx-1 (26% identical), Caenorhabditis elegans jmjd-3.1 (16% identical), Caenorhabditis elegans jmjd-3.2 (13% identical), Caenorhabditis elegans jmjd-3.3 (12% identical). Paralogues in human: KDM6A (86% identical), KDM6B (30% identical).
Diseases named in the same sentence as UTY in open-access papers:
UTY is named in the same sentence as 39 diseases in open-access papers, as found by Europe PMC text mining. Sharing a sentence is not in itself a finding about the gene and the disease. The quoted sentences say what the papers report.
prostate carcinoma (5 papers, 2023 to 2026). A carcinoma that arises from epithelial cells of the prostate gland. "While direct functional validation remains limited in several cancer types, UTY is increasingly implicated as a potential tumour suppressor in haematological malignancies and prostate cancer." (PMID 42201147, 2026). "Through pseudo-time analysis, we traced the dynamic trajectory of tumor cells from primary prostate cancer to bone metastasis, highlighting the crucial role of UTY and USP9Y in this process." (PMID 40299503, 2025). "Additionally, we identified key genes co-expressed with UTY and USP9Y, offering insights into potential therapeutic targets for bone metastasis in prostate cancer." (PMID 40299503, 2025). "Other six genes, including upregulated JARID2, JMJD4, and RIOX2, as well as downregulated HIF1AN, HR, and UTY were not reported in prostate cancers so far." (PMID 36776320, 2023).
acute myeloid leukemia (3 papers, 2021 to 2026). Acute myeloid leukemia (AML) is a group of neoplasms arising from precursor cells committed to the myeloid cell-line differentiation. "Unlike frequently mutated UTX in cancers such as breast, renal cell carcinoma, and acute myeloid leukaemia, UTY's contributions in cancer are less defined, constrained by male-specific expression." (PMID 42201147, 2026). "Moreover, genes KDM5D, UTY, and NF1 have demonstrated gender differences in lung cancer, while PPP6C and IGF1R exhibit sex-biased expression in melanoma, and the NRAS gene may play sex-specific roles in acute myelogenous leukemia." (PMID 39541191, 2024).
atherosclerosis (3 papers, 2019 to 2023). A disease characterized by the build-up of fatty material and calcium deposition in the arterial wall resulting in partial or complete occlusion of the arterial lumen. "This suggests that UTY can at least partly mediate the effect of haplogroup I1 on gene expression programmes and that some of them may be related to suppression of immunity and increased susceptibility to atherosclerosis." (PMID 31644355, 2019).
bladder cancer (3 papers, 2016 to 2025). "In clinical practice, detecting the loss of KDM5D and UTY could serve as valuable prognostic indicators, aiding in assessing the clinical aggressiveness of bladder cancer and guiding treatment decisions." (PMID 39594721, 2024). "This underscores the potential significance of assessing the expression of ChrY genes, particularly UTY and KDM5D, as a means of identifying bladder cancer patients who may benefit from ICI therapy in order to achieve improved response rates and enhanced survival outcomes." (PMID 39594721, 2024).
coronary artery disease (3 papers, 2014 to 2018). "This predisposition to coronary artery disease was shown to be associated with the down-regulation of UTY genes (amongst others) in macrophages." (PMID 26335491, 2015).
pancreatic cancer (3 papers, 2019 to 2023). "A study in pancreatic cancer found that concurrent loss of UTY and KDM6A in male patients was associated with a more malignant phenotype and poorer and prognosis." (PMID 34220955, 2021). "In addition, UTY is frequently lost or mutated in pancreatic tumors with squamous differentiation in male patients." (PMID 37198323, 2023). "Hence this study suggests that KDM6A and UTY have tumor-suppressive roles in pancreatic cancer and that sex-specific mechanism should be investigated in melanoma and other cancers." (PMID 34220955, 2021). "In addition, male mice that expressed UTY and female mice with heterozygous KDM6A expression exhibited a less aggressive pancreatic cancer phenotype, while male and female mice with no UTY or KDM6A exhibited a more aggressive malignant phenotype." (PMID 34220955, 2021).
developmental delay (2 papers, 2012 to 2025). "Given the widespread developmental delay and pleiotropy, it is difficult to assess the primary defect and tissue(s) responsible for UTX and UTY redundancy." (PMID 23028370, 2012).
Infertility (2 papers, 2017 to 2019). "So, this study might be helpful in understanding the effect of missense mutation on protein function of UTY in relation with infertility in men." (PMID 29062794, 2017). "Our findings implicate Y-chromosomal genes, including USP9Y, UTY, TXLNGY, RBMY1B, RBMY1E, RBMY1J and TSPY4, some of which are known to be important for spermatogenesis, in the curative hormonal treatment of cryptorchidism-induced infertility." (PMID 31171972, 2019).
male infertility (2 papers, 2017 to 2023). The inability of the male to effect fertilization of an ovum after a specified period of unprotected intercourse. "However, there is no significant amount of polymorphism studies on UTY which is waiting for extensive studies based on population and clinical screening which may affect male infertility." (PMID 29062794, 2017). "Considering the role played by UTY gene in male infertility, the study aimed to narrow down the candidate non-synonymous SNPs (nsSNPs) for the UTY through computational analysis which may influence the protein structure and/or function that may serve an important role in male infertility." (PMID 29062794, 2017).
urothelial bladder cancer (2 papers, 2016 to 2020). "In urothelial bladder cancer (UBC), 22.8% (8/35) of patients were found to have a reduced UTY copy number, and cell proliferation was found to increase in a UTY knockout." (PMID 33381555, 2020).
acute lymphoblastic leukemia (1 paper, 2017). Leukemia with an acute onset, characterized by the presence of lymphoblasts in the bone marrow and the peripheral blood. "In consistent with our observations, a recent study also showed that UTY cannot compensate for certain demethylase-dependent activities of UTX in T cell acute lymphoblastic leukemia (T-ALL)." (PMID 28970783, 2017).
Alzheimer disease (1 paper, 2023). A progressive, neurodegenerative disease characterized by loss of function and death of nerve cells in several areas of the brain leading to loss of cognitive function such as memory and language. "The expression of histone H1.5, encoded by the UTY and HIST1H1B genes, may impact genes associated with the pathophysiology of Alzheimer’s disease." (PMID 37628788, 2023).
Autoimmunity (1 paper, 2016). The occurrence of an immune reaction against the organism's own cells or tissues. "UTY demethylates the repression-associated modified histone H3K27me3, whereas KDM5D demethylates the activation-associated modified histone H3K4me3, a prominent target for anti-nuclear autoimmunity in female (NZW×B6.Lbric)F1 mice." (PMID 27483354, 2016).
colorectal cancer (1 paper, 2019). A primary or metastatic malignant neoplasm that affects the colon or rectum. "Whether UTY also promotes the development of colorectal cancer by participating in the regulation of KIF14 expression requires further research." (PMID 31139021, 2019). "Therefore, considering the difference in incidence of colorectal cancer between different sexes, it is important to study the role of UTY in colorectal cancer." (PMID 31139021, 2019).
Constipation (1 paper, 2024). Infrequent or difficult evacuation of feces. "The present results suggest that C3 deficiency-induced constipation may be associated with 1237 upregulated genes including PNLIP, CEL, CPB1, CTRL, PNLIPRP1, and REG1 as well as 1292 downregulated genes including Eif2s3y, UTY, KDM5D, IGKV6-32, Olfr870, and DDX3Y." (PMID 39273477, 2024).
COVID-19 (1 paper, 2023). A disease caused by infection with severe acute respiratory syndrome coronavirus 2. "Examination of the top DEGs enriched and depleted in male versus female COVID-19 Mo/DCs revealed appropriate recovery of Y-linked genes (DDX3Y, EIF1AY, and UTY) and XIST, which enables X chromosome inactivation and, thus, is increased in female cells." (PMID 37606044, 2023).
gonadoblastoma (1 paper, 2024). A mixed germ cell/sex cord-stromal tumor characterized by the presence of large germ cells which resemble seminoma cells and small cells which resemble Sertoli or granulosa cells. "According to reports, deletion of the UTY gene in the AZFa region may result in the complete absence of male germ cells, and that UTY is also of GBY the overlapping gonadoblastoma susceptibility Y region." (PMID 39850494, 2024).
lymphoma (1 paper, 2018). A malignant (clonal) proliferation of B- lymphocytes or T- lymphocytes which involves the lymph nodes, bone marrow and/or extranodal sites. "Given that in male mice UTY may partially compensate for UTX loss, we analyzed lymphomas from UTX wild-type and UTX-knockout female mice." (PMID 30006524, 2018). "Notably, Eμ-Myc;UTX−/y mice developed lymphoma with complete penetrance, whereas only 50% of Eμ-Myc;UTX+/− single knockout mice developed lymphoma, further arguing that UTY could not provide significant compensation for UTX during tumorigenesis." (PMID 30006524, 2018).
neuroblastoma (1 paper, 2021). Neuroblastoma (NB) is the most common solid, extracranial childhood tumor. "We then compared the RNA-seq transcript counts of KDM6B, KDM6A, and UTY in three large neuroblastoma cohorts and found that expression of KDM6B was significantly higher than that of KDM6A or UTY." (PMID 34893606, 2021). "To determine whether high expression of KDM6B in neuroblastoma is associated with active epigenetic modifications, we investigated the epigenetic landscapes at the genomic loci of KDM6B, KDM6A, and UTY in seven primary human neuroblastoma tissues sequenced at St." (PMID 34893606, 2021). "In summary, KDM6B is highly expressed in human neuroblastoma and its genomic locus is epigenetically modified for active gene transcription, which is distinct from its paralogs KDM6A and UTY." (PMID 34893606, 2021). "We also found that levels of KDM6B expression, but not KDM6A or UTY, in neuroblastoma cell lines were among the highest, across 40 different cancer lineages." (PMID 34893606, 2021). "We have previously shown that KDM6B, but not KDM6A or UTY, is essential for neuroblastoma cell survival." (PMID 34893606, 2021).
osteoarthritis (1 paper, 2024). A noninflammatory degenerative joint disease occurring chiefly in older persons, characterized by degeneration of the articular cartilage, hypertrophy of bone at the margins and changes in the synovial membrane. "Further data analysis validated that these genes (TK1, CD300A, EGFR, and UTY) are correlated with the immune microenvironment of Osteoarthritis." (PMID 38549939, 2024). "We used deep machine learning algorithms, including the LASSO and SVM algorithms, to identify four candidate feature genes in Osteoarthritis cases: TK1, CD300A, EGFR, and UTY." (PMID 38549939, 2024). "However, the roles of TK1, CD300A, and UTY in Osteoarthritis have not yet been reported." (PMID 38549939, 2024).
pancreatic ductal adenocarcinoma (1 paper, 2026). An infiltrating adenocarcinoma that arises from the epithelial cells of the pancreas. "Emerging evidence suggests UTY as a context-dependent tumour suppressor in AML and squamous-like pancreatic ductal adenocarcinoma." (PMID 42201147, 2026).
pulmonary hypertension (1 paper, 2025). Increased pressure within the pulmonary circulation due to lung or heart disorder. "Furthermore, UTY is also known to protect against pro-inflammatory phenotypes in lung tissue during pulmonary hypertension." (PMID 40073144, 2025).
teratoma (1 paper, 2020). A non-seminomatous germ cell tumor characterized by the presence of various tissues which correspond to the different germinal layers (endoderm, mesoderm, and ectoderm). "UTY is essential in the development of teratoma through the regulation of epigenetic changes." (PMID 33381555, 2020).
tumor (19 papers, 2014 to 2026). "Second, in vitro functional studies, particularly under androgen deprivation therapy (ADT) conditions, can clarify how UTY or USP9Y loss affects tumor cell proliferation, apoptosis, invasion, and organoid-forming capacity." (PMID 40299503, 2025). "Nonsynonymous mutations were found in the genes AMELY, DDX3Y, RPS4Y2, TBL1Y in African tumors (5 samples: 4 HRPCa 1 LRPCa), and in UTY in one European HRPCa tumor." (PMID 40454088, 2025). "Here, we found nonsynonymous variants impacting AMELY, DDX3Y, RPS4Y2, and TBL1Y in five African tumors (4.7%), and UTY in a single European tumor (1.8%), highlighting the potential for these chrY genes as ancestry-specific cancer driver candidates." (PMID 40454088, 2025). "Regarding the tumor-suppressive genes of the ChrY associated with cancer initiation events, TMSB4Y and KDM5D are the most noteworthy but the UTY gene possesses some tumor suppressive activity as well and is worth mentioning." (PMID 41214505, 2025). "Relative to UTX, male-specific UTY exhibited a weaker tumor-suppressive activity in the leukemia models." (PMID 36821650, 2023). "The unavailability of UTX−/− mice, as well as the potential compensation by UTY complicates the study of UTX’s role as tumor suppressor." (PMID 30006524, 2018). "Although demethylase activity was not investigated in our study, loss of either UTX or UTY increased proliferation, indicating that UTX and UTY likely act as tumor suppressors in a dose-dependent manner." (PMID 27533081, 2016). "In addition, our study identified two Y chromosome-linked genes, UTY and USP9Y, which are highly expressed in PCa bone metastases and are strongly associated with tumor cell proliferation, metastasis, and immune evasion." (PMID 40299503, 2025). "UTY encodes a histone demethylase that is capable of epigenetically regulating AR (androgen receptor) target genes such as PTEN, thereby potentially promoting tumor cell proliferation." (PMID 40299503, 2025). "KDM6A and UTY have significant tumor suppressor activity in several types of cancer." (PMID 40949882, 2025). "Additionally, the precise identification of the molecular pathways linking the loss of UTY and/or KDM5D to CD8+ T cell fatigue within the tumor microenvironment is crucial for advancing our understanding and developing targeted therapeutic strategies." (PMID 39594721, 2024). "UTY is the Y chromosome homolog of UTX with weaker tumor-suppressive activity compared to UTX." (PMID 37198323, 2023). "The seven genes comprising the HMR model (SUZ12, KAT2A, AURKA, BUB1, SUV39H2, UTY, and PCGF5) are critically involved in epigenetic modification, tumor progression, supporting their prognostic value in MM." (PMID 40949882, 2025). "Knock-out of both UTX and UTY increased UBC cell proliferation, suggesting that UTY acts as a tumor suppressor in UBC." (PMID 27533081, 2016). "While UTX escapes X chromosome inactivation in females, UTY may function as the male homologue of UTX, which could compensate for dosage imbalances and maintain the tumor suppressive effects in males." (PMID 27533081, 2016). "To evaluate the functional roles of UTX and UTY in tumor progression, we designed UTX and UTY single knockout and UTX-UTY double knockout experiments using a CRISPR/Cas9 lentiviral system, and compared the proliferative capacities of two UBC cell lines in vitro." (PMID 27533081, 2016). "In normal kidney tissue ANKS1B, ACOT6, EYS, CHRNA6, MT1G and UTY were up regulated in smokers in comparison to non-smokers; however, these genes tended to be down regulated in smokers versus non-smokers in ccRCC tumor tissue." (PMID 24479813, 2014). "While deletion of the UTY IDR reduced its tumor-suppressive activity, replacing it with the IDR of UTX significantly enhanced UTY’s activity; conversely, replacing the IDR of UTX with that of UTY significantly reduced UTX’s tumor-suppressive activity, pointing out an important role for IDR." (PMID 36821650, 2023).
tumor (continued). "UTY may not fully compensate for the role of UTX to suppress tumor cell proliferation, but simultaneous loss of UTX and UTY might drive carcinogenesis." (PMID 27533081, 2016).
cancer (13 papers, 2016 to 2026). A tumor composed of atypical neoplastic, often pleomorphic cells that invade other tissues. "Therapeutically targeting UTY's scaffold functions shows promise for male-specific cancers and merits future investigation." (PMID 42201147, 2026). "Genomic loss of UTY in male cancer cell lines with inactivating UTX mutations (13/16, 81%) is significantly more frequent than UTY loss in UTX wild-type cancers (153/307, 49%)." (PMID 37198323, 2023). "The ubiquitously transcribed tetratricopeptide repeat Y-linked gene (UTY/KDM6C), a catalytically impaired histone demethylase encoded on the Y chromosome, has garnered increasing attention for its emerging roles in tumorigenesis and cancer progression." (PMID 42201147, 2026). "Moreover, several confirmed gender-related carcinogenic genes exhibit completely different distributions in male and female cancer samples, such as PIK3CA, NF1, EIF1AY, IGF1R, NRAS, KDM5D, UTY, and PPP6C." (PMID 39541191, 2024). "In such examples, UTY could be functional, but UTY mutations can also occur, and complete loss of the Y chromosome is not uncommon in males with a KDM6A mutation in cancer." (PMID 35406676, 2022). "The role of UTY in cancer cell proliferation has not been elucidated." (PMID 27533081, 2016). "However, recent studies provide evidence that UTX and UTY do share some functional redundancy, refuting the assumption that UTY is a nonfunctional remnant of UTX, and play an important role in differentiation, development, and pathophysiology, including cancer and heart disease." (PMID 38030664, 2023).
UTY also shares sentences with these, for which no sentence is quoted: Azoospermia (2 papers); autism spectrum disorder (1); clear cell renal cell carcinoma (1); cryptorchidism (1); gastric cancer (1); liver cancer (1); lung carcinoma (1); melanoma (1); myeloid malignancies (1); Obesity (1); prostate tumor (1); renal cell carcinoma (1); T-cell acute lymphoblastic leukemia (1); viral infections (1).